TRAF6 (TNF receptor associated factor 6)
Diseases named in the same sentence as TRAF6 in open-access papers (continued):
Sharing a sentence is not in itself a finding about the gene and the disease.
glioma (15 papers, 2015 to 2025). A benign or malignant brain and spinal cord tumor that arises from glial cells (astrocytes, oligodendrocytes, ependymal cells). "There was an inverse correlation between the expressions of miR-146b-5p and TRAF6, implying that miR-146b-5p downexpression was an important cause leading to TRAF6 overexpression in gliomas." (PMID 26320176, 2015). "Mechanistically, we verified TRAF6 as a direct functional target of miR-146b-5p, which facilitated our understanding of the mechanisms underlying glioma malignant progression." (PMID 26320176, 2015). "Another study revealed that IRGM promotes glioma development by regulating the p62/TRAF6/NF-κB pathway, resulting in increased IL-8 production and M2 macrophage polarization." (PMID 40959082, 2025). "A recent study showed that TRAF6 overexpression was positively correlated with glioma grade and Ki-67 index, which in turn predicted poorer prognosis in glioma patients." (PMID 26769849, 2016). "MiR-146b was reported to suppress glioma cell proliferation and induce apoptosis by targeting TRAF6, and predict the prognosis of glioma patients." (PMID 27185265, 2016). "The glioma subgroups with higher level of miR-146b-5p and lower level of TRAF6 were correlated with better prognoses, suggesting that miR-146b-5p and TRAF6 were the specific biomarkers for the prognostic-based glioma subclassification." (PMID 26320176, 2015). "Most importantly, we found that miR-146b-5p and TRAF6, not only were correlated with each other, but also predicted the survival of glioma patients, highlighting the potential values of miR-146b-5p and TRAF6 as novel prognostic biomarkers in human gliomas." (PMID 26320176, 2015). "Pearson analysis confirmed that Ki-67 LIs were negatively correlated with miR-146b-5p LIs (r = −0.980, P < 0.0001) and positively correlated with TRAF6 LIs (r = 0.984, P < 0.0001) in gliomas." (PMID 26320176, 2015). "Our findings identify miR-146b-5p as a tumor suppressor and novel prognostic biomarker of gliomas, and suggest miR-146b-5p and TRAF6 as potential therapeutic candidates for malignant gliomas." (PMID 26320176, 2015). "We discovered that TRAF6 expression in gliomas was higher than that in the control (P < 0.05 ∼ 0.001) and that its expression was significantly increased with the elevation of glioma grades and was the highest in glioblastoma (P < 0.01 ∼ 0.001)." (PMID 26320176, 2015). "In summary, our study revealed that miR-146b-5p inhibited the proliferation of glioma cells and promoted their apoptosis in vitro and in vivo by directly targeting TRAF6, and predicted better prognosis in human gliomas, especially in glioblastoma." (PMID 26320176, 2015). "Interestingly, miR-146b-5p can suppress tumor cell progression and downregulate TRAF6 by improving the chemotherapy resistance of gliomas." (PMID 37909731, 2023). "The second-best hit, miR-146b, is a known tumour-suppressor targeting TRAF6 in gliomas." (PMID 33806327, 2021). "Moreover, TRAF6 expression was positively correlated with glioma grades and Ki-67 index but inversely correlated with miR-146b-5p expression and predicted poor prognosis of glioma patients." (PMID 26320176, 2015). "Moreover, TRAF6 expression in gliomas was negatively correlated with miR-146b-5p expression (r = −0.997, P < 0.0001)." (PMID 26320176, 2015). "Furthermore, a homograft nude mouse model was explored and mice transplanted with TRAF6/IRAK1-overexpressing glioma cells had shorter survival times while mice transplanted with glioma cells with miR-146a-5p overexpression or TRAF6/IRAK1 knockdown lived longer." (PMID 37391426, 2023). "To further determine the underlying mechanisms by which miR-146b-5p suppresses gliomas, we focused on TAK1 and IκBα, the important downstream effectors of TRAF6, to investigate whether they were responsible for the suppressed proliferation and increased apoptosis induced by miR-146b-5p." (PMID 26320176, 2015).
glioma (continued). "Thus, miR-146b-5p and TRAF6 could be the novel and clinical feasible candidates for diagnosis and subclassification for gliomas." (PMID 26320176, 2015). "Our results reveal that miR-146b-5p downexpression and TRAF6 overexpression are responsible for excessive proliferation and reduced apoptosis of glioma cells, whereas both upregulation of miR-146b-5p and knockdown of TRAF6 may effectively reverse the malignant phenotype of glioblastoma cells." (PMID 26320176, 2015). "Since the miRNA data of GBM patients were not available in TCGA database, we analyzed the correlation of miR-146a-5p vs. TRAF6 and vs. IRAK1 in the Chinese Glioma Genome Atlas (CGGA) database." (PMID 37391426, 2023). "We used TRAF6 and IRAK1 as a gene set and evaluated its effect on the survival time of glioma patients in TCGA." (PMID 37391426, 2023). "The correlation between TRAF6 and IRAK1 was evaluated with immunofluorescence (IF)-stained clinical glioma samples." (PMID 37391426, 2023). "Phosphorylated DCBLD2 can recruit TRAF6 and stimulate the AKT pathway, promoting the migration and invasion abilities of glioma cells." (PMID 33579282, 2021). "Kaplan-Meier analyses demonstrated that the high level of TRAF6 expression predicted a short-term DFS (P < 0.0001) and OS (P < 0.0001) in glioma patients." (PMID 26320176, 2015). "The protein levels of TRAF6 and IRAK1 were estimated with IF-stained glioma samples." (PMID 37391426, 2023). "Since other target genes, such as MMP16 and EGFR, were also involved in the modulation induced by miR-146b-5p, the prognostic significance of TRAF6 was not as important as that of miR-146b-5p in gliomas." (PMID 26320176, 2015). "Our multivariate analysis showed that TRAF6 was not an independent prognostic factor for DFS and OS of glioma patients, but univariate analysis demonstrated that TRAF6 could act as an auxiliary prognostic biomarker of patients’ survival." (PMID 26320176, 2015). "Multivariate analysis showed that TRAF6 was not an independent predictor for DFS and OS of glioma patients." (PMID 26320176, 2015).
systemic lupus erythematosus (15 papers, 2010 to 2026). An autoimmune multi-organ disease typically associated with vasculopathy and autoantibody production. "Here, we show that TANK, a negative regulator of the NF-κB signaling via suppression of TRAF6 ubiquitination, is critical for the amelioration of fatal DAH caused by lung vascular endothelial cell death in a mouse model of systemic lupus erythematosus." (PMID 34819357, 2022). "Circulating exosomal miRNA-146a may inhibit lupus-induced inflammation through down-regulation of TRAF6 and regulate IFN production." (PMID 39660463, 2025). "Because exosomes in the blood might protect miRNAs, the association between circulating exosomal miRNA-146a and lupus proinflammatory genes, such as IRAK1 and TRAF6, was studied in peripheral blood mononuclear cells from people with JSLE." (PMID 38355214, 2024). "In summary, this study was the first to report that circulating exosomal miRNA-146a in patients with JSLE might inhibit lupus-induced inflammation through TRAF6 downregulation." (PMID 38355214, 2024). "In imiquimod-induced lupus mouse model, imiquimod activated TLR7 receptor, activating downstream MyD88 and TRAF6, and releasing mitochondrial dsDNA and dsRNA through MyD88 and TRAF6 to further activate of MDA5 and cGAS pathways in splenic B cells." (PMID 39917309, 2025). "In systemic lupus erythematosus (SLE),miR-146a expression was decreased, while IRAK1 and TRAF6 expressionremained unchanged." (PMID 41552448, 2026).
multiple myeloma (14 papers, 2013 to 2024). "In vitro studies have shown that increased TRAF6 expression is positively associated with enhanced myeloma cell proliferation." (PMID 38169510, 2024). "SiRNA of TRAF6 inhibited the proliferation and promoted the apoptosis on myeloma and multiple myeloma (MM) cells." (PMID 37005742, 2023). "Evidence is accumulating that TRAF6 inhibited osteoclast formation and promoted the proliferation of multiple myeloma cell lines and bone resorption." (PMID 37005742, 2023). "The adhesion of multiple myeloma cells to bone marrow stromal cells leads to activation of tumor-promoting signaling pathways, while TRAF6 promotes adhesion through NF-κB-induced adhesion factors." (PMID 32905356, 2020). "Decreases expression of TRAF6 at both protein and mRNA level leading to inhibition of osteoclasts maturation and function in peripheral blood mononuclear cells (PBMCs) of multiple myeloma patients." (PMID 28579943, 2017). "For example, whether the regulation of miR-361-3p targeting TRAF6 on the biological functions of multiple myeloma is related to other genes or pathways still needs further studying in vitro and in vivo." (PMID 33323675, 2021). "Plasma cells from multiple myeloma patients express PD-L1 and increase expression after stimulation with IFN-γ and TLR ligands via a myeloid differentiation primary response gene 88/tumor necrosis factor receptor associated factor 6 (MYD88/TRAF6)-, MEK-dependent pathway." (PMID 28484456, 2017). "An early study in multiple myeloma cells showed that IFN‐γ promoted PD‐L1 expression through a MyD88‐, TRAF6‐ and MEK‐dependent pathway, and IFN‐γ activated transcription factor STAT1 partially via the MEK/ERK pathway." (PMID 28218497, 2017). "B7-H1 expression was enhanced on malignant plasma cells from multiple myeloma patients by IFN-γ and Toll-like receptor stimulation via MEK/ERK-dependent and MyD88/TRAF6-dependent pathways and can inhibit T-cell responses." (PMID 23737812, 2013). "The relationship between the type of myeloma and the level of mir-361-3p or TRAF6 was not studied in this article, which might be a limitation and should be studied more in the future." (PMID 33323675, 2021).
psoriasis (14 papers, 2018 to 2025). An autoimmune condition characterized by red, well-delineated plaques with silvery scales that are usually on the extensor surfaces and scalp. "NFKBIZ is a psoriasis susceptibility gene that encodes the functions of TRAF6 signalling players, especially in terms of positive and regulatory immune controls by interactions between immune cells and epithelial cells." (PMID 36925653, 2023). "Consistently, many psoriasis susceptibility genes encode the TRAF6 signaling players, such as ACT1 (TRAF3IP2), A20 (TNFAIP3), ABIN1 (TNIP1), IL-36Ra (IL36RN), IkappaBzeta (NFKBIZ), and CARD14." (PMID 31156649, 2019). "For example, miR-146 targets key adaptor molecules TRAF6 and IRAK1 in TLR/NFκβ mediated immune response pathways and high expression of this miRNA has been reported in Psoriasis causing inflammatory disorder." (PMID 38146363, 2023). "It is illustrated that miR-155 regulates Act1/TRAF6/NF-κB by targeting A20, and Ebosin regulates IL-17 pathway and Th17/Treg imbalance by miR-155 in psoriasis." (PMID 33981308, 2021). "Key nodes such as STAT3, TRAF6, and PTEN emerged, showing convergence on inflammatory signaling, keratinocyte proliferation, and immune regulation, which represent core pathogenic mechanisms in psoriasis." (PMID 41458345, 2025). "On the other hand, patient 2 and 3 shared SNPs in NFKBIZ and in TNFAIP3, encoding the IL-17/TRAF6 signaling regulators IKB-ζ and A20, respectively, whose genetic variability could contribute to immune dysregulation and chronic inflammation in psoriasis lesions." (PMID 38495872, 2024). "Reportedly, allicin directly inhibits the IL-17A/F-induced STAT3/NF-κB and TRAF6/MAPK/NF-κB signaling cascades in keratinocytes, thereby attenuating pro-inflammatory feedback and ameliorating psoriasis-like dermatitis." (PMID 40871078, 2025). "Then, which of the TRAF6 pathways, NF-κB pathways or MAP kinase pathways, is essential for the development and persistence of psoriasis?" (PMID 38312837, 2024). "Oroxylin A has been demonstrated to demonstrate remarkable precision by specifically targeting the critical p62-TRAF6 interface to effectively block TRAF6 oligomerization and K63 ubiquitination, thereby inhibiting the NF-κB/NLRP3 inflammatory axis in psoriasis models." (PMID 41562074, 2025). "Therefore, TRAF6-dependent p38-MAP kinase-mediated transcriptional activation of keratinocytes is expected to generate the necessary and sufficient conditions for psoriasis." (PMID 38312837, 2024). "Therefore, the unbalanced homeostasis of the TRAF6 signaling pathways with attenuated NF-κB activation and dominant MAPK activation in the epidermis might contribute to triggering type 17 innate response and giving rise to the increased susceptibility to psoriasis." (PMID 31156649, 2019). "Moreover, TRAF6-null keratinocytes were resistant to the stimulation with either imiquimod or IL-17 in vitro, with subsequent absence of their psoriasis mediators for DC recruitment and activation." (PMID 31156649, 2019). "Therefore, IL-36–TRAF6 signaling in keratinocytes might be a critical event in this animal model and human psoriasis while the production of IL-36α/β/γ is not so affected in imiquimod-induced dermatitis in mice lacking TRAF6 in keratinocytes." (PMID 31156649, 2019).
Autoimmunity (13 papers, 2012 to 2025). The occurrence of an immune reaction against the organism's own cells or tissues. "Traf6-ΔT mice suffer from autoimmunity associated with enhanced activation of Tconv effector cells that are unresponsive to the suppression of Treg cells." (PMID 36761777, 2023). "For instance, TRAF6‐deficient mice are prone to autoimmunity suggesting a key role in the regulation of immune activation." (PMID 30886050, 2019). "Transferring liver T cells into immunodeficient mice recapitulates AIH symptoms, confirming that TRAF6 directly regulates mTEC development to impact self-reactive T cells and autoimmunity." (PMID 38562929, 2024). "Vice versa, TRAF6 is essential for autoimmunity upon MALT1 protease inactivation in T cells, emphasizing the critical interdependency of MALT1 and TRAF6 to balance T cell activation and homeostasis." (PMID 36761777, 2023). "Here we demonstrate that ablation of TRAF6 in T cells induces autoimmunity via T cell-intrinsic activation of MALT1 substrate cleavage." (PMID 36761777, 2023). "Instead TRAF6[L74H] mice display an entirely different phenotype, exhibiting autoimmunity, and severe inflammation of the skin and modest inflammation of the liver and lungs." (PMID 35157702, 2022). "Thus, in order to provide evidence that loss of TRAF6 induces autoimmunity through cell-intrinsic MALT1 protease activation, we generated mice in which TRAF6 deletion and MALT1 protease inactivation are combined specifically in T cells." (PMID 36761777, 2023). "C25-140 decreases TRAF6 activity, reduces NF-κB activation, and combats autoimmunity." (PMID 36550542, 2022). "Our results demonstrate firstly down-regulated pulmonary miR-146a levels with increased TRAF6 and IL-8 expression and NETs and apoptosis formation in autoimmune-mediated DAH, and implicate a therapeutic potential of intra-pulmonary miR-146a delivery in such patients." (PMID 36028828, 2022). "Previously, global TRAF6 knockout was found to precipitate multi‐organ autoimmunity." (PMID 30886050, 2019). "Since autoimmunity frequently leads to glomerulonephritis, we studied the kidney pathology, but no glomerulonephritis or any other pathological changes in the kidney were detected in 16-day-old TRAF6[L74H] mice, perhaps because the mice were too young for this phenotype to have developed." (PMID 35157702, 2022). "The onset of autoimmunity and autoinflammation in TRAF6[L74H] mice (two weeks) was much faster than in mice with a Treg-specific knockout of TRAF6 or lacking TRAF6 expression in all T cells (2–3 months) and we discuss whether this may be caused by secondary inflammation of other tissues." (PMID 35157702, 2022). "A more recent study showed a direct correlation between TRAF6 SNPs and SLE, supporting the notion that TRAF6 is potentially involved in the pathogenesis of autoimmune conditions." (PMID 23227085, 2012). "By combining TRAF6 ablation and MALT1 paracaspase inactivation selectively in T cells, we provide genetic evidence that T effector responses and autoimmunity in the absence of TRAF6 relies on MALT1 protease activation." (PMID 36761777, 2023). "The TRAF6[L74H] mice develop autoimmunity, skin and liver inflammation within 16 days, while mice with a specific knock-out of TRAF6 in Tregs or all T cells do not develop these phenotypes until they are 8–11 weeks old." (PMID 35157702, 2022). "Thus, Treg specific TRAF6 deletion resulted in allergy and SLE-like autoimmunity, although the diseases were slightly milder than in whole T cell-specific TRAF6 deletion." (PMID 24058613, 2013). "In this study the absence of TRAF6 or mutations in MALT1 impairing the interaction with TRAF6, enhanced the T cell activation independent protease activity of MALT1 and caused flagrant autoimmunity in mice." (PMID 35251035, 2022).
Autoimmunity (continued). "Like the TRAF6[L74H] mice, mice lacking TRAF6 in Tregs or all T cells have enlarged lymph nodes, display splenomegaly, generate GCB cells spontaneously, have elevated serum levels of a variety of antibodies and develop autoimmunity and multiorgan inflammation including dermatitis." (PMID 35157702, 2022).
ischemic stroke (13 papers, 2019 to 2026). A stroke disorder caused by obstruction of blood flow to the brain, due to thrombotic (local blood clot formation) or embolic (due to a blood clot or other material traveling from another site) event. "For example, MSC-derived exosomal miR-146a-5p inhibited neuro-inflammation and neurological deficits by inhibition of the interleukin 1 receptor associated kinase 1 (IRAK1)/TNF receptor associated factor 6 (TRAF6) pathway in ischemic stroke." (PMID 36552117, 2022). "miR-146a-5p improved neural deficits following ischemic stroke by downregulating microglia-induced neuroinflammation via the IRAK1/TRAF6 pathway." (PMID 36361891, 2022). "In summary, we have found that NOD2 stimulation mediated robust and broad inflammatory response in microglia and ARRB2 negatively regulated NOD2‐induced inflammatory response following ischaemic stroke by combination with TRAF6." (PMID 30793522, 2019). "This miRNA regulates the NLRP3 inflammasome by targeting TRAF6 and may become a novel therapeutic target for ischemic stroke." (PMID 38361743, 2024). "Exosomal miR-146a-5p derived from human umbilical cord mesenchymal stem cells could attenuate microglia-mediated neuroinflammation via the IRAK1/TRAF6 pathway and subsequent neural deficits following ischemic stroke." (PMID 35548775, 2022). "In addition, other studies identified that Sirtuin 1 and reactive oxygen species play a significant role in TRAF6-mediated neuronal damage after stroke, and TRAF6 inhibition displayed neuroprotective effects in ischemic stroke via mitigating oxidative stress and neuroinflammation." (PMID 38267979, 2024). "Targeting EZH2 methyltransferase activity has been proven to be effective in multiple neuroinflammatory diseases, such as neuropathic pain, ischemic stroke and early brain injury (EBI), revealing a cross-talk between EZH2 and TRAF6/NF-κB pathway." (PMID 37391829, 2023). "Moreover, miR-31 from ADSC-derived extracellular vesicles (EVs) has been shown to downregulate the expression of TRAF6 and IRF5, leading to reduced ischemic stroke-induced neuronal damage." (PMID 35454994, 2022).